ID1 (inhibitor of DNA binding 1)
Diseases named in the same sentence as ID1 in open-access papers (continued):
Sharing a sentence is not in itself a finding about the gene and the disease.
tumor (continued). "Secondly, the inhibition of miR-29b causes the increasing expression of DNA binding 1 (ID1) and MMP9, which lead to tumor cell invasion." (PMID 27391030, 2016). "In total, 13 of 17 mice treated with a BMP inhibitor showed an increase in Id1 promoter activity in the tumor." (PMID 27048361, 2016). "ID1 has been a hot topic in cancer research for years, and numerous cancer cells are reported to overexpress ID1, which is in relation to tumor angiogenesis." (PMID 27127787, 2016). "Id-1 is a transcription factor that prevents tumor cell differentiation and its expression is elevated in highly aggressive tumors." (PMID 27774065, 2016). "Taken together, our results indicate that CDC27 contributes to CRC cell proliferation via the modulation of ID1-mediated p21 regulation, which offers a novel approach to the inhibition of tumor growth." (PMID 26821069, 2016). "The reduction in tumor size was accompanied by decreased expression of Id-1 and Sox-2 indicating a reduction in tumor aggressiveness." (PMID 27774065, 2016). "The effect of the BMP receptor inhibitors DMH2 and LDN-193189 (LDN) to regulate Id1 expression in tumor xenografts was examined." (PMID 27048361, 2016). "Targeting of Id1 transcription blocks EPC mobilization, causes angiogenesis inhibition, impairs the spread of metastasis, and increases the survival of tumor-bearing mice." (PMID 27071670, 2016). "The anchorage-independent tumor growth by Id1 overexpression was also abrogated by long-term treatment with FH535 in these cells." (PMID 25938540, 2015). "Tumours from Id1-overexpressing mice had a significant increase in volume compared with control vector mice on day 21 (2.2-fold)." (PMID 25924227, 2015). "In these cells, the ability for anchorage-independent tumor growth was also positively regulated by Id1." (PMID 25938540, 2015). "Our study reveals for the first time a novel pivotal role for Id1 in tumour and metastatic progression and in controlling systemic tumour-induced immunosuppression, providing further insight into the therapeutic promise of Id1 targeting." (PMID 25924227, 2015). "In patient tumor samples, ID1 expression also was found to correlate with Src activation, poor tumor differentiation, and reduced overall survival." (PMID 26264026, 2015). "Here, we show that in the case of BMDCs, TGFβ is the primary tumour-derived factor responsible for Id1 upregulation, as its neutralization largely abrogates Id1 expression in vitro." (PMID 25924227, 2015). "Targeting of Id1 or downstream pathways would provide a three-pronged therapeutic approach by reducing metastatic potential of the tumour itself, reducing tumour angiogenesis and finally restoring systemic immune function." (PMID 25924227, 2015). "We found that DCs isolated from non-tumour mice expressed very low to undetectable Id1, whereas Id1 expression was higher in MDSCs from tumour-bearing mice compared with both control MDSCs (3.2-fold) and DCs from tumour-bearing mice (11.2-fold)." (PMID 25924227, 2015). "To further investigate the role of Id1 in primary tumour and metastatic progression, we transplanted Lin− BM cells from Id1−/− or WT BM into lethally irradiated WT recipients to generate BM chimeric mice." (PMID 25924227, 2015). "This study reveals a critical role for Id1 in suppressing the anti-tumour immune response during tumour progression and metastasis." (PMID 25924227, 2015). "This suggests the Src-ID1 axis to be an important component in nicotine-mediated tumor promotion as well as a clinically relevant prognostic marker." (PMID 26264026, 2015). "We demonstrate that Id1 upregulation is responsible for generating an immunosuppressive macroenvironment and driving tumour progression." (PMID 25924227, 2015). "This is the first study to implicate Id1 in the crosstalk between tumours and the host immune system via regulation of myeloid cell differentiation." (PMID 25924227, 2015).
tumor (continued). "Lungs of Id1-overexpressing mice had a 13-fold increase in metastatic tumour cells compared with the lungs of control vector-transplanted mice." (PMID 25924227, 2015). "When we assessed the immune function of Id1-overexpressing tumour-bearing mice, we found similar DC numbers but significantly elevated MDSC (P<0.01), T-reg numbers (P<0.001) and ROS production compared with control vector tumour-bearing mice." (PMID 25924227, 2015). "In light of our results, we propose the use of Id1 and its mediators as biomarkers of systemic immune dysfunction during tumour progression as well as candidates for targeted anti-tumour therapeutic strategies." (PMID 25924227, 2015). "To further validate the role of Id1 in impairing myeloid differentiation in response to tumour-derived factors, we used the BMDC assay using Id1−/− cells." (PMID 25924227, 2015). "In this study, we identify Id1 as a novel pivotal regulator of the switch from DC differentiation to MDSC expansion during tumour progression." (PMID 25924227, 2015). "Id1 expression has been shown to promote tumor angiogenesis by increasing endothelial progenitor cell formation." (PMID 24516656, 2014). "Id1 has been shown to trigger the xenograft tumor growth in nude mice via the regulation of the PI3K/Akt and NF-κB/Survivin pathways." (PMID 24572994, 2014). "The in vivo data from our previous studies indicate that both Id1 and NF-κB are highly expressed in the edge of xenograft tumor lumps and are highly proliferative in vitro." (PMID 24572994, 2014). "Among the most downregulated proteins, we found several confirmed or candidate tumour suppressor genes (eg, ID1, FAS, FPR1, IL10, PCGF2, VDR)." (PMID 25594007, 2014). "With increased tumorigenicity in a subcutaneous xenograft model, we next sought to verify that overexpression of both COX-2 and Id1 would also enhance tumorigenicity in an orthotopic tumor model." (PMID 24659686, 2014). "Thirdly, COX-2 overexpression promotes important GBM phenotypes including tumor angiogenesis and invasive potential at least in part through induction of Id1." (PMID 24659686, 2014). "Expression levels are generally decreased in adult organs and are increased with inflammation and tumor formation where Id1 and Id3 have been shown to have a key role in promoting angiogenesis." (PMID 24516656, 2014). "Tumor growth in the untreated Id1-GFP-overexpressing group (Id1-OE, O4) occurred at a faster rate than that in the untreated vector control group (Id1-EV, P7)." (PMID 25344919, 2014). "It is noted that Id1 is expressed in the entire xenograft tumor lump whereas NF-κB is in the edge of xenograft tumors." (PMID 24572994, 2014). "The weight of tumor in the Id1-suppressed group was dramatically decreased by 4.1- and 6.6-fold, and that in the Id1 and Id3 double knockdown group by 6.8- and 10.9-fold." (PMID 25061504, 2014). "Our results showing the tumor promoting functions of ID1 are also supported by a recent report showing that ID1 promotes NSCLC cell migration." (PMID 25028095, 2014). "Some previous studies have demonstrated that both Id1 and Id3 promoted malignant progression of certain types of cancers through facilitating angiogenesis, a crucial feature of tumor development and progression." (PMID 25061504, 2014). "The Id1 and 3 proteins have a critical role in promoting angiogenesis during development, tumor growth and wound repair by functioning as dominant negative regulators of bHLH transcription factors." (PMID 24516656, 2014). "These tumor-promoting functions of ID1 appear to be brought about by STMN3 and GSPT1, which are up regulated by ID1." (PMID 25028095, 2014). "In the nude mice xenograft model, the tumor growth was reduced to a large degree in the Id1-overexpressing group upon treatment with paclitaxel and cisplatin." (PMID 25344919, 2014). "In fact, high Id1 levels correlate strongly with poor prognosis, chemoresistance and tumor metastases." (PMID 24659686, 2014).
tumor (continued). "Clinical and mechanistic evidence supports that GCIP exerts its tumor-suppressive function in NSCLC through suppression of Id1-triggered oncogenic properties." (PMID 24970809, 2014). "In this study, we demonstrated that GCIP transcriptionally inhibited Id1 expression and exerted antagonistic effects on Id1-driven tumor progression of NSCLC." (PMID 24970809, 2014). "Knockdown of ID1 and ID3 expression in metastasizing cells results in a failure to initiate MET and dramatically reduces lung colonization, providing strong evidence that ID proteins are required for the maintenance and propagation of disseminated tumor cells." (PMID 25927844, 2014). "A comparison of Id1 and Id3 expression between primary tumor and matching metastatic tissues should be also investigated." (PMID 23311395, 2013). "Most tumors showed moderate levels of Id1, most likely originating from the Id1 produced by endothelial cells within the vasculature of the tumor." (PMID 23691228, 2013). "Generally, ID1 contributes to tumorigenesis by inhibiting cell differentiation, stimulating proliferation, enhancing invasion and facilitating tumor neoangiogenesis." (PMID 24137437, 2013). "In the present study, also for the first time, tumor cell blocks and cytology smears have been included for Id1 and Id3 immunostaining analysis." (PMID 23311395, 2013). "The importance of ID1 in promoting tumor invasion and metastasis has emerged and a role as a possible molecular marker of tumor aggressiveness has been proposed." (PMID 24137437, 2013). "The effect of ID1 silencing on cell proliferation was also investigated, as this contributes to tumor invasion." (PMID 24137437, 2013). "As shown in a bone marrow transplant model with Id1+/-Id3-/- tumor-resistant mutant mice, transplanted bone marrow endothelial and hematopoietic precursor cells are fully capable of supporting tumor growth." (PMID 23676470, 2013). "Id1 is mainly expressed in cancer cells, but is occasionally seen in epithelial basal cells and proliferating fibroblasts surrounding the tumor cells." (PMID 23714001, 2013). "In conclusion, the present study suggests that the tumor co-expression of Id1 and Id3 can be a powerful prognostic biomarker in a selected subgroup of stage III-N2 NSCLC patients receiving definitive chemoradiotherapy." (PMID 23311395, 2013). "We also found that tumor cells in PDICs specifically were positive for Id3, another Id family member which can play a redundant role to Id1." (PMID 23691228, 2013). "We stained tissue sections from RT2 mice and found that Id1 was expressed in all endothelial cells within tumors, which was expected as Id1 has been shown to play an important role in tumor angiogenesis." (PMID 23691228, 2013). "Strikingly, we found that the majority of tumor cells in PDICs specifically stained for Id1, exhibiting a nuclear staining pattern." (PMID 23691228, 2013). "In Id1 knock-out mice, it appeared that tumor growth was significantly inhibited due to an angiogenesis defect." (PMID 23714001, 2013). "More interestingly, the co-expression of both proteins Id1 and Id3, in the same tumor samples, showed a significant inverse correlation with OS in those patients showing a clinical stage considered of worse prognosis (cT4N2 disease)." (PMID 23311395, 2013). "Inhibitor of DNA binding 1 (Id1) and 3 (Id3) genes have been related with the inhibition of cell differentiation, cell growth promotion and tumor metastasis." (PMID 23311395, 2013). "The importance of ID1 in promoting tumor invasion and metastasis has recently emerged and a role for ID1 as a possible molecular marker of tumor aggressiveness has been proposed." (PMID 24137437, 2013). "We acknowledge Kelly Dunlap for monitoring tumorigenesis in Id1 transgenic mice and collecting tumor samples and Flora Ling for critical reading to the manuscript." (PMID 22393458, 2012).
tumor (continued). "Taken together, it appears that Notch activation provides Id1-expressing tumor cells with selective advantages in growth and survival." (PMID 22393458, 2012). "The tumor-promoting properties of Id1, Id2, and Id3 are at least partially shared by Id4 also: Id4 has been shown to promote neoplastic transformation/growth." (PMID 23342267, 2012). "Our study shows that Notch activities are clearly advantageous for lymphomagenesis in Id1 transgenic mice, probably through enhanced survival and/or proliferation of tumor cells." (PMID 22393458, 2012). "By comparing levels of best-known Notch target genes and incidences of gain-of-function events in Id1 and N1C-expressing tumor samples, we conclude that a large fraction of Id1-expressing tumors exhibit evidence of significant Notch activation." (PMID 22393458, 2012). "Contrary to these observations, studies have also demonstrated pro-tumor function of Id4 that is consistent with its other family members Id1, Id2, and Id3." (PMID 23342267, 2012). "A similar trend was noted for ID1, where in all patients low expression of the gene was associated with a shortest RFS, but in the CCND1 low ER-positive subgroup of tumours, a positive correlation was found." (PMID 21955753, 2011). "For instance ZNF382, a KZNF also known as KS1, has recently been identified as a tumor suppressor controlling a number of oncogenes including ID1." (PMID 21876767, 2011). "We also seek to determine the functional significance of Id1 expression in NSCLC development and progression using in vitro model systems for tumor cell growth and migration using lentiviral-mediated constitutively expressed Id1." (PMID 20414347, 2010). "In order to evaluate the influence of Id1 expression on NSCLC tumor cell growth, normal H23 cells (NI) and H23 cells transduced with lentivirus expressing GFP alone (GFP) or GFP-Id1 (Id1) were evaluated in an MTS proliferation assay." (PMID 20414347, 2010). "Our in vitro analysis of Id1 function in NSCLC cell lines indicates that although most tumor cells expressed a high level of Id1 when cultured in media containing 10% serum, most Id1 expression in these tumors is growth factor dependent and not constitutive." (PMID 20414347, 2010). "We found variable expression of Id1 in the tumor cell lines evaluated with highest expression in H520, H1299, U1752, and H460." (PMID 20414347, 2010). "To address the physiological role of Id1 in mammary development and neoplasia, we generated a transgenic mouse overexpressing Id1 under the control of the tetracycline regulatory element (TRE-Id1 strain)." (PMID 20689821, 2010). "It has also been shown that Id1 and Id3 overexpression correlates with loss of CDKN2A expression in different tumours, suggesting that in some settings Id1/3-induced cell proliferation is mediated through the inactivation of the CDKN2A-pRb pathway." (PMID 20842131, 2010). "Functional assays were performed to evaluate the role of Id1 in tumor cell growth, migration and progression." (PMID 20414347, 2010). "In various forms of tumours, Id1 and Id3 are overexpressed extensively and in an overlapping pattern." (PMID 20842131, 2010). "Our finding that LMP1 expression in primary NPC tumours correlates with reduction of activated Foxo3a in the nucleus and increased expression of Id1 corroborates findings obtained from our in vitro studies." (PMID 20565867, 2010). "Tumours also exhibited significantly increased expression of ID1 and profound down-regulation of S100A8, highlighting their potential as therapeutic targets for OS." (PMID 20551950, 2010). "Id-1 also confers tumour cells resistance to radio- and chemotherapy-induced apoptosis through the activation of PI3K/Akt/NF-κB signalling pathways." (PMID 19240717, 2009). "It is likely that the reduced levels of survival signalling pathways activated by RT in P529-treated mice (i.e., Akt, VEGF, Id-1, and MMPs) end up in a reduced proliferation/apoptosis ratio in vivo, leading to tumour shrinkage." (PMID 19240717, 2009).
tumor (continued). "The overexpression of Id-1 in tumour cells results in an increased cell proliferation and tumour angiogenesis through the upregulation of VEGF." (PMID 19240717, 2009). "Constitutive expression of Id1 from the lck proximal promoter leads to tumorigenesis with the age of 50% tumor free survival being 20 weeks." (PMID 19688092, 2009). "Previously, we reported that tumor growth was inhibited more effectively in Id1+/−, Id3−/− than in Id1+/−, Id3+/+ mice." (PMID 19956687, 2009). "Tumour cells showed positive staining for Id-1 in 43 cases (93.5%), for EGFR in 41 cases (89%) and for VEGF in 42 cases (91%)." (PMID 19014499, 2008). "In this study, using immunohistochemical methods, we investigated the relationship between Id-1 and such well-known prognostic factors as tumour grade and tumour stage and such molecules as EGFR and VEGF." (PMID 19014499, 2008). "This study is, to our knowledge, the first to reveal that ID-1 expression in the cancer cells increased with tumour advancement of uterine cervical cancers." (PMID 19002177, 2008). "G III tumours had the highest degree of staining for Id-1, while the degree of staining was lower in G I tumours." (PMID 19014499, 2008). "To conclude, this study suggests that ID-1 promotes tumour advancement of uterine cervical cancer through angiogenesis, leading to poor prognosis, and provides a novel therapeutic approach in uterine cervical cancers." (PMID 19002177, 2008). "There was a significant relation between the tumour grade and the degree of staining for Id-1, EGFR and VEGF." (PMID 19014499, 2008). "The helix-loop-helix transcription factor Id-1 (an inhibitor of differentiation and DNA binding) plays a role in development and progression of many tumours." (PMID 19014499, 2008). "But contrary to their finding, present study showed that mostly diffuse to strong cytoplasmic expression of ID-1 in tumour cells and also very weak ID-1 expression in endothelial cells." (PMID 19002177, 2008). "Regarding tumour cell proliferation, ID-1 inhibited the promoter region of the tumour suppressor gene CDKN2A/p16, supporting the role of ID-1 as a potential oncogene." (PMID 19002177, 2008). "The relation between the tumour stage and the degree of staining for Id-1, EGFR and VEGF was also significant." (PMID 19014499, 2008). "In accordance with the restored tumor growth observed in the Id1-/- p21-/- mice, the tumors taken from these animals showed a normal vascular density." (PMID 18092003, 2007). "As previously reported, Id1-/- mice showed a slower rate of tumor growth compared to wild type mice (80% less growth seen 7 days after implantation p<0.001)." (PMID 18092003, 2007). "It has been known for several years that depletion of the dominant negative helix-loop-helix protein Id1 in mice leads to a failure of tumor angiogenesis and consequently a significant delay in tumor growth." (PMID 18092003, 2007). "To demonstrate that the Id1-/- p21-/- Lin- Flk-1+ cKit+ cells were functionally able to sustain tumor angiogenesis we analyzed the rate of tumor growth in the Id1-/- p21-/- mice." (PMID 18092003, 2007). "In lines with these results, we found that primary ESCC at M1 stage had a significantly (P=0.012) higher nuclear expression of Id-1 than the M0 stage tumours." (PMID 18000500, 2007). "Quantitative real time PCR and western blot analysis confirmed that Id1 is upregulated in BM progenitor cells in response to tumor growth further demonstrating that angiogenesis stimulates Id1 expression in a small subset of BM progenitor cells." (PMID 18092003, 2007). "Genetic ablation of p21 rescues the EPC population in the Id1 null animals, re-establishing functional BM-derived angiogenesis and restoring normal tumor growth." (PMID 18092003, 2007). "Loss of Id1 in the BM leads to a complete loss of the EPC population in the peripheral blood, which has been correlated with a block in tumor neovascularization and delayed tumor growth." (PMID 18092003, 2007).